SFTPB (surfactant protein B)
Description:
Pulmonary surfactant-associated proteins promote alveolar stability by lowering the surface tension at the air-liquid interface in the peripheral air spaces. SP-B increases the collapse pressure of palmitic acid to nearly 70 millinewtons per meter.
Synonyms: SP-B; SFTP3; PSP-B; SFTB3; SMDP1
Tractability: Antibody: its Gene Ontology location is reachable by antibodies, with high confidence; UniProt places it where antibodies can reach, with medium confidence; UniProt predicts a signal peptide or a membrane-spanning region.
Gene: Protein-coding gene on chromosome 2 (85,655,154 to 85,668,741, reverse strand). Ensembl gene ENSG00000168878.
Subcellular location: Secreted, extracellular space, surface film
Pathways (Reactome):
Disease: Defective CSF2RA causes SMDP4; Defective CSF2RB causes SMDP5; Defective pro-SFTPB causes SMDP1 and RDS
Metabolism of proteins: Surfactant metabolism
Gene Ontology:
Molecular function: protein binding
Biological process: animal organ morphogenesis; respiratory gaseous exchange by respiratory system; lipid metabolic process; sphingolipid metabolic process
Cellular component: alveolar lamellar body; clathrin-coated endocytic vesicle; endoplasmic reticulum membrane; extracellular region; lamellar body; multivesicular body; multivesicular body lumen; cytoplasm; lysosome
Genetic constraint (gnomAD): Loss-of-function variants: 32 observed, 50.83 expected, observed/expected ratio (o/e) 0.63, 90% interval 0.47 to 0.85. The upper end of that interval is the gene's LOEUF score, 0.85, which puts it in group 3 of 6, group 1 being the genes least tolerant of losing a copy. Missense variants: 431 observed, 491.32 expected, observed/expected ratio (o/e) 0.88, 90% interval 0.81 to 0.95. Synonymous variants: 211 observed, 204.43 expected, observed/expected ratio (o/e) 1.03, 90% interval 0.92 to 1.16.
Gene-disease validity (ClinGen):
ClinGen rates the evidence that SFTPB causes each of these diseases.
surfactant metabolism dysfunction, pulmonary, 1 (autosomal recessive): Definitive.
Homologues: Orthologues: chimpanzee SFTPB (99% identical), macaque SFTPB (91% identical), dog SFTPB (73% identical), guinea pig SFTPB (72% identical), mouse Sftpb (71% identical), rabbit SFTPB (70% identical), rat Sftpb (69% identical), pig SFTPB (67% identical), tropical clawed frog sftpb (31% identical), Drosophila melanogaster Sap-r (22% identical), Caenorhabditis elegans spp-10 (15% identical), zebrafish sftpbb (15% identical), and 1 more. Paralogues in human: PSAP (26% identical), PSAPL1 (22% identical).
Diseases named in the same sentence as SFTPB in open-access papers:
SFTPB is named in the same sentence as 116 diseases in open-access papers, as found by Europe PMC text mining. Sharing a sentence is not in itself a finding about the gene and the disease. The quoted sentences say what the papers report.
lung carcinoma (35 papers, 2002 to 2025). "Pro-SFTPB is associated with early lung cancer and is elevated in the blood circulation of people at high risk of lung cancer, but the exact mechanism is not clear." (PMID 37476198, 2023). "Among the top 10 differentially expressed genes are others that are linked to pulmonary biology and/or lung cancer (SFTPB, SLIT2, TNKS)." (PMID 28445992, 2017). "Our study provides population-level evidence confirming the causal relationship between reduced SFTPB protein levels and NSCLC risk, suggesting that SFTPB agonists could be a promising avenue for therapeutic prevention in high-risk individuals with lung cancer." (PMID 41049426, 2025). "Lung cancer may therefore present an appealing target for therapeutic prevention as high-risk individuals who may benefit from such interventions are readily identifiable if a suitable agonist for SFTPB can be identified." (PMID 38684708, 2024). "Further, there were significant differences in serum Pro-SFTPB (P = 0.007) levels among benign lung disease and early lung cancer." (PMID 37476198, 2023). "For example, some studies have shown that high expression of pro-SFTPB is a predictor of lung cancer and that it correlates with lymph node metastasis in NSCLC." (PMID 37946295, 2023). "It has been previously reported that there is a significant and independent correlation between plasma Pro-SFTPB and lung cancer, and it also plays a predictive role in lung cancer." (PMID 37476198, 2023). "In this study, we first systematically analyzed the expression of eight AT II-associated genes (AQP4, SFTPB, SFTPC, SFTPD, CLDN18, FOXA2, NKX2-1, and PGC) in lung cancer." (PMID 36203529, 2022). "In this study, we comprehensively analyzed the gene expression, prognosis value, genetic alteration, and immune cell infiltration of eight AT II-associated genes (AQP4, SFTPB, SFTPC, SFTPD, CLDN18, FOXA2, NKX2-1, and PGC) in Nonsmall Cell Lung Cancer (NSCLC)." (PMID 36203529, 2022). "Among the lung-associated genes, SFTPB and SFTPD were highly specific to the lung, as demonstrated by the four tissue RNA samples, and they were solely found in lung cancer LM patients’ CSF." (PMID 34625644, 2021). "A recent study suggested using the expression of SFTPB as a prognostic marker for lung cancer patients." (PMID 33166290, 2020). "Surfactant proteins have been extensively studied in relation to various lung diseases, and surfactant protein A2, surfactant protein B and surfactant protein D have been studied as serum lung cancer or lung disease biomarkers." (PMID 22515324, 2012). "SFTPB was also an independent biomarker for lung cancer diagnosis." (PMID 41423496, 2025). "In particular, low expression of pro-SFTPB may be related to the metastasis and recurrence of lung cancer, but further confirmation is needed, and the molecular mechanism of this effect is still unclear." (PMID 37946295, 2023). "Several studies have shown that the serum expression level of pro-surfactant protein B (pro-SFTPB) is increased in patients with lung cancer, with a poor prognosis and shorter survival, thus indicating a diagnostic and prognostic role of serum pro-SFTPB in detecting human cancer." (PMID 37511463, 2023). "However, the imbalance of SFTPB synthesis in lung cancer cells leads to the over-expression of Pro-SFTPB." (PMID 37476198, 2023). "Indeed, lung cancer cells show dysregulated SFTPB synthesis with the overexpression of pro-SFTPB and an inability to post-translationally modify the precursor into the mature SP-B form." (PMID 37511463, 2023). "For instance, promoter regions of Human kallikrein 2(KLK2) in prostate, Apolipoprotein A1 (APOA1) in liver, NK6 homeobox 3 (NKX6.3) in stomach, paired box gene-8 (PAX-8) in kidney, and Surfactant Protein B (SFTPB) in lung cancers were among the selected markers from our pipeline." (PMID 35729208, 2022).
lung carcinoma (continued). "Interestingly, a recent report showed that both nondetectable status and high levels of plasma pro-SFTPB are significantly associated with lung cancer risk." (PMID 37946295, 2023). "Moreover, pro-SFTPB in plasma, the precursor of SFTPB, was an independent predictor of lung cancer." (PMID 33542901, 2020). "Over the past l0 years, a significant amount of research data has accumulated on other promising biomarkers for lung cancer detection: autoimmune antibody signature (Autoantibody signature, AAB), micro-RNA and pro-surfactant Protein B (Pro-SFTPB)." (PMID 40458730, 2025). "Especially, five lung cancer-related genes including CYP4B1, CHRDL1, SFTPC, SFTPB, and AGER were consistently downregulated in both LUAD and LUSC had a positive correlation with TMPRSS2, exhibited an opposite effect on the prognosis of LUAD and LUSC." (PMID 35082790, 2021). "In addition to genes associated with smoking the AC1/AC2 classifier included several genes implicated in lung cancer tumorigenesis, such as KITID1MMP7MYCNXRN2, and CYP24A1, as well as type II pneumocyte marker genes such as NKX2-1 (TTF1/TITF1), LAMP3 (CD208), and surfactant proteins SFTPB and SFTPC." (PMID 22676229, 2012). "Additionally, we identified SFTPB (OR: 0.93, 95% CI 0.91–0.95), ICAM5 (OR: 0.95, 95% CI 0.93–0.97), and FLRT3 (OR: 1.10, 95% CI 1.05–1.15) as potential targets for lung cancer." (PMID 37735436, 2023). "This study aimed to assess a four-marker protein panel (4MP)’s performance, including the precursor form of surfactant protein B, cancer antigen 125, carcinoembryonic antigen, and cytokeratin-19, for predicting lung cancer in a cohort enriched with never- and ever-smokers." (PMID 38893188, 2024). "The serum levels of SFTPB were specifically increased in ILD cases but not in other respiratory diseases, such as bronchial asthma (BA), chronic obstructive pulmonary disease (COPD), and lung cancer." (PMID 38855869, 2024).
respiratory failure (33 papers, 2002 to 2024). The significant impairment of gas exchange within the lungs resulting in hypoxia, hypercarbia, or both, to the extent that organ tissue perfusion is severely compromised. "Changes in the expression of the SFTPB gene can cause pulmonary inflammation and severe respiratory failure, both through changes at the DNA level and through epigenetic changes." (PMID 38203821, 2024). "Infants homozygous for recessive loss-of-function mutations in SFTPB develop respiratory failure and die shortly after birth." (PMID 39000201, 2024). "Pathogenic variants in this gene give rise to a rare form of progressive respiratory failure, which is linked to changes in surfactant production, structure, and balance, influencing the expression of associated genes, including SFTPB, SFTPC, and ABCA3." (PMID 38203821, 2024). "In SFTPB deficiency, symptoms occur a short time after delivery, usually in term newborns, and progress to refractory respiratory failure and death or need for lung transplantation in the first months of life." (PMID 39457702, 2024). "Congenital PAP is an inherited disease where the affected fetus unfortunately dies within the first months of life due to deficiency of surfactant protein B (SP-B), causing imbalanced surfactant homeostasis and function, which leads to respiratory failure." (PMID 35893099, 2022). "We focused our attention on surfactant protein B, because SP-B is necessary for the formation of the active surface film, it is essential for life and an association of SP-B variants with acute respiratory failure in COPD was demonstrated." (PMID 12107845, 2002). "While mutations in SFTPB and ABCA3 cause a significant disruption in surfactant production and respiratory failure in newborn infants, mutations in SFTPC and SFTPA usually clinically emerge later, in infancy or in adulthood." (PMID 39000201, 2024). "Surfactant protein B (SFTPB), a major component of pulmonary surfactant, is strictly required for breathing, and its absence is associated with lethal respiratory failure in humans." (PMID 37946295, 2023). "Mutations in the genes encoding SP-B (SFTPB) and SP-C (SFTPC) have been identified as pathogenic factors in full-term infants with refractory respiratory failure after birth." (PMID 33490270, 2021). "Surfactant protein B knock out mice show disruption of surfactant film and function and die from respiratory failure." (PMID 12107845, 2002). "Knockout of the SFTPB gene can lead to fatal respiratory failure and atelectasis in mice." (PMID 34206713, 2021). "Lung delivery of surfactant protein B (SP-B) mRNA protected mice from respiratory failure, whereas myocardial injection of RNAiMAX-formulated mRNA, encoding human vascular endothelial growth factor A (VEGF-A), improved heart regeneration after myocardial infarction in mice." (PMID 28655327, 2017). "One large study examining 120 children with respiratory failure requiring intubation found lower levels of tracheal aspirate surfactant protein A (SP-A) and surfactant protein B (SP-B) relative to total aspirate fluid protein in pneumonia and ARDS patients compared with controls." (PMID 27313995, 2016). "Mutations in human SFTPB (surfactant associated protein B), and ABCA3 (ATP-binding cassette, sub-family A (ABC1), member 3) genes cause severe lung disease in new-borns, often resulting in respiratory failure at birth." (PMID 22916088, 2012). "Recently, mutations in the ABCA3 transporter were found as an underlying cause of fatal respiratory failure in neonates without surfactant protein B deficiency." (PMID 15819986, 2005).
lung disease (30 papers, 2005 to 2026). "Maternal asthma is associated with increased rates of neonatal lung disease, and fetuses from asthmatic ewes have fewer surfactant‐producing cells and lower surfactant‐protein B gene (SFTPB) expression than controls." (PMID 39436639, 2024). "Surfactant Protein B (SP-B) is an essential component for lung surfactant function since mutations can result in fatal lung disease." (PMID 36327300, 2022). "Both gene addition and gene editing strategies are compared to best design treatments for lung diseases resulting from pathogenic variants in the SFTPB, SFTPC, and ABCA3 genes." (PMID 35098209, 2021). "Patients heterozygous for SFTPB mutations may also benefit from gene therapy as lung disease can develop when other factors reduce their remaining SP-B levels." (PMID 32764559, 2020). "Pathogenic variants in genes responsible for SFTPB and ABCA3 lead to severe and frequently fatal lung diseases, usually inherited in autosomal recessive patterns." (PMID 38203821, 2024). "Pathogenic variants in genes associated with SFTPB and ABCA3 result in severe and often fatal lung diseases, typically inherited in an autosomal recessive manner." (PMID 38203821, 2024). "Several genetic variants have been identified for SFTPA1, SFTPA2, SFTPB, SFTPC, and SFTPD that are associated with pulmonary diseases." (PMID 33469544, 2020). "Several genes associated with monogenetic lung disorders were also dysregulated in specific cell populations of smokers, including PCD (OFD1 – down-regulated in ciliated cells) and surfactant deficiency (SFTPB - up-regulated in ionocytes)-related genes." (PMID 32727470, 2020). "Surfactant protein B (SP-B) is important for optimal surfactant function, since it is involved in the pathogenesis of pulmonary disease." (PMID 23596483, 2013). "In summary, a single SNP of the SFTPB is a marker for mild pulmonary disease in CF." (PMID 30333828, 2018). "While the mature SFTPB is too hydrophobic to circulate in the bloodstream, immature SFTPB proteins are less hydrophobic, and are detectable in the serum, where they might serve as biomarkers for pulmonary diseases with alveolar or interstitial damage, such as ILDs and especially IPF." (PMID 38855869, 2024). "Likewise, SNPs located in this region may affect NKX2-1-binding and in turn influence the expression of SFTPB, thereby modifying the lung disease severity." (PMID 33980985, 2021). "A number of intergenic interactions that all include SNPs of SFTPB as well as a single intragenic SFTPA1 and SFTPA2 interaction are likely to be markers for mild and moderate/severe pulmonary disease in CF, respectively." (PMID 30333828, 2018). "Although, the level of SP-B (encoded by SFTPB) was unchanged in BAL from CF patients, in CF patients with mild lung disease SP-B was found to be increased, but SP-A did not change." (PMID 30333828, 2018).
respiratory distress syndrome (27 papers, 2002 to 2025). "SFTPB contributes to surface tension reduction at the lung air–liquid interface; newborn babies bearing SFTPB mutations develop respiratory distress syndrome." (PMID 38855869, 2024). "Biallelic loss-of-function variants in SFTPB result in full-term infants with severe respiratory distress syndrome, which is typically lethal within the first few months after birth." (PMID 35121658, 2022). "Surfactant protein B (SPB) deficiency is a severe monogenic interstitial lung disorder that leads to loss of life in infants as a result of alveolar collapse and respiratory distress syndrome." (PMID 33426150, 2021). "Inherited deficiency of surfactant protein B (SFTPB) is a rare genetic cause of lethal respiratory distress syndrome in full-term newborn infants." (PMID 31530844, 2019). "Interestingly, SFTPB deficiency in newborns can lead to lethal respiratory distress syndrome." (PMID 40370699, 2025). "Among them, only Curosurf® encapsulated surfactant protein B and C (SP-B and SP-C) in a conventional liposome for the treatment of respiratory distress syndrome (RDS) in premature infants." (PMID 33918072, 2021). "Optimal functionality of synthetic lung surfactant for treatment of respiratory distress syndrome in preterm infants largely depends on the quality and quantity of the surfactant protein B (SP-B) peptide mimic and the lipid mixture." (PMID 34686153, 2021). "Bi-allelic loss-of-function mutations of SFTPB, the gene encoding surfactant protein-B (SP-B) and ABCA3, which encodes ATP-binding cassette transporter A3 (ABCA3) typically present as lethal respiratory distress syndrome in neonates." (PMID 21867529, 2011).
interstitial lung disease (14 papers, 2013 to 2025). A diverse group of lung diseases that affect the lung parenchyma. "Recently, we described a new cell culture platform based on H441 cells that are grown at the air-liquid interface to produce the SALI culture model, for studying and correcting the rare interstitial lung disease surfactant protein B (SPB) deficiency." (PMID 34977273, 2022). "SFTPB mutations are most associated with severe respiratory failure in newborns, while mutations in the other surfactant-related genes are implicated in both adult and pediatric forms of interstitial lung disease, particularly pulmonary fibrosis." (PMID 39768847, 2024). "Notably, deficiency in SP-B or SP-C due to genetic mutations in SFTPB or SFTPC cause hereditary forms of childhood interstitial lung disease." (PMID 34161347, 2021). "Mutations in SFTPA1, SFTPA2, SFTPB, and SFTPC—excluding SFTPD—are recognized as monogenic causes of interstitial lung disease." (PMID 39768847, 2024).
lung adenocarcinoma (11 papers, 2003 to 2024). A carcinoma that arises from the lung and is characterized by the presence of malignant glandular epithelial cells. "We found that higher SFTPB was associated with a lower risk of lung adenocarcinoma." (PMID 38684708, 2024). "Napsin A is an aspartic proteinase involved in the maturation of surfactant protein B. It is detected in the cytoplasm of type 2 pneumocytes and alveolar macrophages and is a putative marker for lung adenocarcinomas." (PMID 23414265, 2013). "Immunohistochemistry was performed for three proteins currently used as markers for lung adenocarcinoma : surfactant protein-A, surfactant protein-B and thyroid transcription factor-1." (PMID 12698189, 2003). "SFTPB is over expressed in non-small cell lung cancer, especially in lung adeno-carcinoma." (PMID 33542901, 2020). "Surfactant protein B (SP-B) has been found to be overexpressed in lung adenocarcinoma." (PMID 27322500, 2016). "A recent study illustrated that SFTPB gene expression was correlated with tumor-infiltrating lymphocytes (TIL), defining an “inflamed” lung adenocarcinoma subtype with favorable survival estimates." (PMID 33802234, 2021). "Surfactant apoproteins, including surfactant protein-A (Sp-A) and surfactant protein-B (Sp-B) are used as markers for lung adenocarcinoma and thyroid transcription factor-1 (TTF-1) is used as a marker for lung adenocarcinoma, large cell carcinoma, small cell carcinoma and thyroid carcinoma." (PMID 12698189, 2003). "Notably, however, we did not observe any associations with other traits for SFTPB, EGFR, and GAS1, which were associated with a lower risk of lung adenocarcinoma and a higher risk of breast cancer overall and triple-negative breast cancer, respectively." (PMID 38684708, 2024). "However, other studies reported that SFTPB is downregulated in lung adenocarcinoma patients with relapse compared to those without relapse, and that low expression of surfactant proteins correlates with a lower overall survival rate in lung adenocarcinoma patients with brain metastasis." (PMID 37946295, 2023).